GALNT7 (polypeptide N-acetylgalactosaminyltransferase 7)
Diseases named in the same sentence as GALNT7 in open-access papers (continued):
Sharing a sentence is not in itself a finding about the gene and the disease.
prostate carcinoma (continued). "Shedding of glycosyltransferases from cells has previously been reported and we recently identified upregulation of the glycosyltransferase enzymes GALNT7 and ST6GAL1 in the blood of prostate cancer patients." (PMID 40387385, 2025). "Analysis of The Cancer Genome Atlas Prostate Adenocarcinoma (TCGA PRAD) cohort revealed a significant correlation between the GALNT7 and FOXO1 genes in clinical prostate cancer tissue." (PMID 36725887, 2023). "Of 31 reciprocally-regulated glycosylation enzymes, a set of 8 (GALNT7, ST6GalNAc1, GCNT1, UAP1, PGM3, CSGALNACT1, ST6GAL1 and EDEM3) were significantly up-regulated in clinical prostate carcinoma." (PMID 27428423, 2016). "Here, urine GALNT7 was 2.5 fold higher in men diagnosed with prostate cancer (compared to men given a ‘no cancer’ diagnosis)." (PMID 36725887, 2023). "GALNT7 was 2.6 fold higher in Likert 3 patients that received a prostate cancer diagnosis compared to men given a ‘no cancer’ diagnosis (p = 0.0001), and GALNT7 was slightly more accurate than serum PSA at identifying men with prostate cancer (serum PSA: AUC = 0.69, urine GALNT7: AUC = 0.78)." (PMID 36725887, 2023). "GALNT7 levels were 7.7 fold higher in urine and 2.1 fold higher in plasma samples from men later diagnosed with prostate cancer compared to men with benign disease or a ‘no cancer’ diagnosis." (PMID 36725887, 2023). "However, how GALNT7 impacts glycosylation in prostate cancer cells has not been previously studied." (PMID 36725887, 2023).
glioma (5 papers, 2020 to 2025). A benign or malignant brain and spinal cord tumor that arises from glial cells (astrocytes, oligodendrocytes, ependymal cells). "The high expression of GALNT7 is related to the poor prognosis of gliomas and can be used as an effective biomarker in gliomas." (PMID 34819077, 2021). "In glioma cells, GALNT7 was co-expressed with several gene including STAT3 which was associated with the JAK-STAT signaling pathway, PVR which participated in the CAMs pathway." (PMID 32308562, 2020).
hepatocellular carcinoma (4 papers, 2012 to 2020). A malignant tumor that arises from hepatocytes. "For example, overexpression of GALNT7 enhanced hepatocellular carcinoma cell proliferation and migration." (PMID 32308562, 2020). "In hepatocellular carcinoma, miR-17-3p was reported to modulate proliferation, migration, survival, morphogenesis and colony formation of HepG2 cells, and it inhibited endothelial tube formation by repressing the expression of vimentin and GalNT7." (PMID 28178677, 2017).
laryngeal carcinoma (4 papers, 2015 to 2024). Carcinoma that arises from the laryngeal epithelium. "For example, up-regulation of the GALNT7 gene has been associated with tumor progression in prostate, cervical, and laryngeal cancers, but has been the subject of only a limited number of studies in terms of ceRNA interactions." (PMID 38627780, 2024). "The expression of GALNT7 in laryngeal carcinoma cells is negatively regulated by miR-34a and miR-34c, thus, playing a tumor inhibitory role." (PMID 34819077, 2021). "GALNT7 also acted as a key contributor of the pro-metastatic effects in laryngeal carcinoma cells." (PMID 32308562, 2020).
laryngeal squamous carcinoma cell (2 papers, 2016 to 2018). "GALNT7, as a downstream target of miR-34a, encoded GalNAc-transferase 7 to participate in laryngeal squamous cell carcinoma." (PMID 29970122, 2018). "Through reduced expression of GALNT7, miR-34a and miR-34c are tumor suppressors in laryngeal squamous carcinoma cell (LSCC), thereby serving as novel potential markers for LSCC therapy." (PMID 27322213, 2016).
papillary thyroid cancer (2 papers, 2021 to 2022). "Overall, miR-30b-5p inhibited the progression of papillary thyroid carcinoma by targeting GALNT7 and inhibiting the EGFR/PI3K/AKT pathway." (PMID 34819077, 2021). "We evaluated the effect of GALNT7 on tumor behavior in PTC, and according to our experimental results, GALNT7 can promote the proliferation and metastasis of papillary thyroid cancer cell lines while silencing the expression of GALNT7 can promote the apoptosis of PTC cells." (PMID 34819077, 2021). "Wang argued that GALNT7 by activating EGFR/PI3K/AKT kinase pathway to promote cell proliferation and invasion of papillary thyroid cancer." (PMID 36276977, 2022).
thyroid cancer (2 papers, 2012 to 2024). "In addition, during thyroid cancer progression, miR-30d-5p inhibits thyroid cancer progression by targeting GALNT7, and GALNT7 has been demonstrated to be a direct and functional target of miR-30b-5p." (PMID 39493373, 2024).
colon cancer (1 paper, 2021). "Alternatively, lncSnhg7 can sequester the microRNA miR-34a resulting in increased expression of GALNT7 promoting colon cancer progression via PI3K/Akt/mTOR signaling." (PMID 35087510, 2021).
esophageal cancer (1 paper, 2022). A primary or metastatic malignant neoplasm involving the esophagus. "Furthermore, overexpression of miR-214-3p resulted in decreased expression of GALNT7, a mediator of extracellular matrix interactions, leading to decreased migratory and invasive abilities of esophageal cancer cell lines." (PMID 36471277, 2022).
leukemia (1 paper, 2021). A malignant (clonal) hematologic disorder, involving hematopoietic stem cells and characterized by the presence of primitive or atypical myeloid or lymphoid cells in the bone marrow and the blood. "Yeoh et al71 also reported a significant loss of GALNT7 mRNA in conjunction with a reduced leukemia burden in B-cell precursor patient samples during the course of initial induction chemotherapy." (PMID 34646384, 2021).
lung carcinoma (1 paper, 2022). "As expected, the silencing of these genes inhibited lung cancer cell proliferation and growth (B3GNT3, GALNT7, PLEK2)." (PMID 35211471, 2022).
mucinous adenocarcinoma (1 paper, 2025). An invasive adenocarcinoma composed of malignant glandular cells which contain intracytoplasmic mucin. "Overall, GALNT7 expression was not consistently associated with age at diagnosis, sex, tumor location, or disease stage, whereas its expression was significantly higher in mucinous adenocarcinomas compared with nonmucinous adenocarcinomas." (PMID 40824763, 2025).
neuroblastoma (1 paper, 2023). Neuroblastoma (NB) is the most common solid, extracranial childhood tumor. "hsa-miR-34a has been reported to regulate ALG13, FUT8, GALNT7, and ST3GAL5 in neuroblastoma and hepatocellular carcinoma." (PMID 37188790, 2023).
prostate adenocarcinoma (1 paper, 2023). "Analysis of RNA sequencing data from The Cancer Genome Atlas Prostate Adenocarcinoma (TCGA PRAD) cohort reveals GALNT7 gene expression levels are 1.9 fold increased in prostate tumours relative to normal prostate tissue (n = 549, p < 0.001)." (PMID 36725887, 2023).
prostate tumours (1 paper, 2023). "We also show that GALNT7 levels remain high in progression to castrate-resistant disease, and using in vitro and in vivo models, reveal that GALNT7 promotes prostate tumour growth." (PMID 36725887, 2023). "Taken together, our data identifies upregulation of GALNT7 as a feature of prostate tumour tissue." (PMID 36725887, 2023). "To test whether GALNT7 is also upregulated at the protein level in prostate tumours, we used immunohistochemistry to monitor GALNT7 protein expression in three independent tissue microarrays (TMA)." (PMID 36725887, 2023).
renal cell carcinoma (1 paper, 2018). "MiR-30a-5p regulated GALNT7 transcripts in renal cell carcinoma." (PMID 29970122, 2018).
sarcopenia (1 paper, 2021). Progressive decline in muscle mass due to aging which results in decreased functional capacity of muscles. "While the effect of GALNT7 and FAIM2 in tumor progression is known (the former favoring and the latter impairing tumor growth), their function in the context of skeletal muscle, exercise and contrast to sarcopenia is less obvious." (PMID 33546468, 2021).
T cell lymphomas (1 paper, 2021). "Surprisingly, miR-34a overexpression did not alter GALNT7 protein levels in EL4 cells, a mouse T cell lymphoma cell line." (PMID 35087510, 2021).
cancer (23 papers, 2012 to 2025). A tumor composed of atypical neoplastic, often pleomorphic cells that invade other tissues. "Lectin arrays and flow cytometry revealed that GALNT7 overexpression correlates with increased binding of SBA lectin (which recognises the cancer-associated Tn antigen)." (PMID 36725887, 2023). "We found that GALNT7, an enzyme that controls the initiation step of protein glycosylation and transfer of N-acetylgalactosamine to serine and threonine amino acid residues, is repressed in late-stage tumours and is implicated in patient survival across cancers." (PMID 39633487, 2024). "In vitro, GALNT7 inhibited reversed the enhanced proliferation, migration, invasion capabilities and even the cancer stem-like cell features due to SPDEF overexpression in luminal BC." (PMID 37633945, 2023). "In cancer cells, miR-30d-5p induces IL-10 expression (an immunosuppressive cytokine), at least in part by repressing the GALNT7 gene, resulting in pro-metastatic effects in vivo." (PMID 36960962, 2023). "Here, we reported the identification of SPDEF which represents a new mechanism of driving cancer stem cell-like properties and tumorigenicity of luminal BC that is mediated by GALNT7." (PMID 37633945, 2023). "We mainly demonstrated that SPDEF transcriptionally activates GALNT7 via directly binding to its promoter to drive cancer stem cell-like properties and tumorigenicity in luminal BC." (PMID 37633945, 2023). "Glycosyltransferase enzymes such as GALNT7 have the potential to be used for the discovery of effective cancer drugs." (PMID 36725887, 2023). "Some glycosylation enzymes (GALNT7, GCNT1, TAP1, PGM3, etc.)are under the control of AR and link to the synthesis of cancer-associated glycans such as sialyl-Tn (sTn), sialyl LewisX (SleX)." (PMID 35853851, 2022). "The abnormal expression of GALNT7 and its family members is related to the occurrence and development of many kinds of malignant tumors." (PMID 34819077, 2021). "Another study in Hep-2 cells demonstrated that miR-34a/c directly regulates UDP-N-acetyl-α-d-galactosamine:polypeptide-N-acetylgalactosaminyltransferase 7 (GALNT7) a member of glycosyltransferases involved in cancer spreading and metastasization." (PMID 32456271, 2020). "These suggested that GALNT7 promoted cancer development by activating the JAK-ATAT or CAMs signaling pathway.Earlier studies also showed that EGF was involved in cell proliferation through activating the EGF receptor (EGFR) signaling pathway." (PMID 32308562, 2020). "GALNT7 expression is on the rise in multiple types of malignant tumors, suggesting that GALNT7 is involved in the occurrence and development of tumors." (PMID 32308562, 2020). "This study also revealed that GALNT7 is the most highly expressed member of the GALNT family, and GALNT7 may be correlated with prognosis in SDC as in other cancers." (PMID 40844495, 2025). "Given that GALNT7 modulates immune-related pathways in multiple cancer types, broader investigations into its role across different tumor contexts may uncover novel insights into its potential as a therapeutic target for immunotherapy." (PMID 40824763, 2025). "Although we found that SPDEF might enhance cancer stem cell-like phenotype and tumorigenesis of luminal BC by activating GALNT7 transcription, there are still some limitations to the current study." (PMID 37633945, 2023). "Moreover, we investigated the relationship between elevated GALNT7 and cancer stem cell-like properties in luminal BC." (PMID 37633945, 2023). "Meanwhile, the direct targeting of GALNT7 by SPDEF was confirmed by restoration of GALNT7 in SPDEF silenced luminal BC cells which successfully reversed the cancer stem cell-like phenotype and oncogenic function in vitro and in vivo, and the other direction is also true." (PMID 37633945, 2023).
cancer (continued). "As one member of the UDP-N-acetyl-α-d-galactosamine:polypeptide N-acetylgalactosaminyltransferase (GalNAc-T or GALNT) family, GALNT7 acts as a glycosyltransferase in protein O-GlcNAcylatio, regulating the interaction between cancer cells and the extracellular environment." (PMID 32308562, 2020). "However, these associations varied substantially by cancer type, suggesting that GALNT7 may exert complex and context-dependent roles in cancer progression and immune regulation." (PMID 40824763, 2025). "Furthermore, we provided evidence that GALNT7 may play a similarly important role in regulating the cancer stem cell-like properties in luminal BC." (PMID 37633945, 2023). "Regarding initiation of GalNAc-type O-glycosylation, GALNT2, GALNT3, GALNT6, GALNT7, and GALNT14 were highly expressed in both cancer types, LUAD and LUSC." (PMID 40718829, 2025). "On the other hand, our analysis showed that the GALNT7, KLF9, and DAB2 genes may be particularly critical as ceRNAs in three cancer tissues." (PMID 38627780, 2024). "More specifically, in this core interaction network, ceRNAs such as GALNT7, KLF9, and DAB2 and miRNAs like miR-106a/b-5p, miR-20a-5p, and miR-519d-3p may have potential as common targets in the three critical cancers." (PMID 38627780, 2024). "The results of the study revealed that the miRNA:ceRNA interaction consisting of 63 genes and 165 miRNAs is common to all three cancer tissues and that the GALNT7, KLF9 and DAB2 genes may be involved in critical ceRNA interactions in all three cancer tissues." (PMID 38627780, 2024). "Overexpression of GALNT7 induces proliferation in various cancer cell lines, but its function has not been reported in normal T cells." (PMID 35087510, 2021). "A recent pan-cancer analysis across 33 cancer types further revealed that GALNT7 expression had either a positive or negative impact on prognosis and tumor immunophenotypes, correlating with immune-related genes, immune-inhibitory genes, and immune cell infiltration." (PMID 40824763, 2025). "Here, we deepened the study on nine of them (ASS1, EIF4G1, GALNT7, GLUT1, IGF2BP3 (IMP3), ITGA4, RAN, SOD1, and THBS2) to ascertain whether they are truly mesothelial cancer driver genes (CDGs) or genes overexpressed in an adaptive response to the tumoral progression (“passenger genes”)." (PMID 32659970, 2020).
tumor (22 papers, 2012 to 2026). "Noteworthy, the combined detection of serum GALNT7 and traditional tumor markers can enhance diagnostic accuracy thus is of vital importance in the early diagnosis of luminal BC." (PMID 37633945, 2023). "Also, the downregulation of GALNT7 caused more apoptosis of tumor cells (P < 0.0001 and P = 0.0006)." (PMID 34819077, 2021). "Importantly, we found that the combined determination of serum GALNT7 and traditional tumor markers (CEA and CA125) could enhance diagnostic accuracy thus is of vital importance in luminal BC." (PMID 37633945, 2023). "However, the underlying mechanism by which GALNT7 promoted tumor progression need further study." (PMID 32308562, 2020). "Collectively, these findings uncover GALNT7 as a critical regulator linking ferroptosis and anti-tumor immunity, providing a mechanistic basis for ferroptosis-based sensitization to ICB therapy in NSCLC." (PMID 42318657, 2026). "In vivo, using nude mouse xenograft and lung metastasis models, we confirmed that GALNT7 overexpression can synergize with NUP50-WT to significantly promote tumor growth and metastasis, while also enhancing the levels of NUP50 and VVA." (PMID 42173248, 2026). "In contrast, supplementation with NUP50-MUT effectively blocked the tumor-promoting effects of GALNT7 overexpression." (PMID 42173248, 2026). "We also examined the relationship between GALNT7 staining and tumor cell PD-L1 positivity, Tn antigen H-score, and infiltration of CD8+ TILs, CD4+ TILs, Foxp3+ TILs, and CD163+ macrophages, stratified by MMR/MSI status." (PMID 40824763, 2025). "GALNT7 is the only gene effector that controls the height of the glycocalyx, and upregulation of GALNT7 alters O‐glycosylation and promotes tumor growth." (PMID 40844495, 2025). "Another enzyme correlating with tumor growth is GALNT7, which has been shown to be an important driver of disease progression." (PMID 39594740, 2024). "Using sub-cutaneous in vivo mouse models, we found that knockdown of GALNT7 significantly suppressed the growth of CWR22RV1 tumours, whereas overexpression of GALNT7 significantly increased the growth of PC3 tumours." (PMID 36725887, 2023). "In fact, GALNT7 is tumor-promoting in cervical carcinoma (targeted by miR-30e and miR-214), esophageal squamous cell cancer (targeted by miR-214), laryngeal carcinoma and colorectal cancer, both targeted by miR-34a." (PMID 36555445, 2022). "Previous reports have suggested that GALNT7 is involved in the regulation of tumor progression through PI3K/Akt/mTOR and EGFR/PI3K/AKT pathways." (PMID 34819077, 2021). "MiR-30b-5p plays the role of the tumor suppressor gene by directly inhibiting the expression of Polypeptide N-Acetylgalactosaminyltransferase 7(GALNT7)." (PMID 34819077, 2021). "As a member of the acetylgalactosaminyltransferase family, GALNT7 materializes a certain biological effect by regulating the interaction between tumor cells and the extracellular environment." (PMID 29970122, 2018). "Depending on the cancer type, GALNT7 displays opposite tumor-promoting or tumor-suppressing activities, and is regulated by different miRNAs." (PMID 28481247, 2017). "GALNT7 promotes tumor growth also in esophageal squamous cell carcinoma, where it is overexpressed because of reduced miR-214." (PMID 28481247, 2017). "In contrast, miR-214 directly targets the GALNT7 gene to suppress growth and invasiveness of cervical cancer cells by functioning as a tumor suppressor a tumor suppressor." (PMID 24465869, 2014). "Moreover, combining GALNT7 depletion with PD-1 blockade achieved synergistic tumor suppression, which is reversed by Ferrostatin-1, indicating ferroptosis-dependent immunostimulation." (PMID 42318657, 2026). "GALNT7 has been reported as a member of the acetylgalactosaminyltransferase family which materializes a certain biological effect by regulating the interaction between tumor cells and the extracellular environment." (PMID 37633945, 2023).